TRBV6-6 (T cell receptor beta variable 6-6)
Description:
V region of the variable domain of T cell receptor (TR) beta chain that participates in the antigen recognition. Alpha-beta T cell receptors are antigen specific receptors which are essential to the immune response and are present on the cell surface of T lymphocytes. Recognize peptide-major histocompatibility (MH) (pMH) complexes that are displayed by antigen presenting cells (APC), a prerequisite for efficient T cell adaptive immunity against pathogens. Binding of alpha-beta TR to pMH complex initiates TR-CD3 clustering on the cell surface and intracellular activation of LCK that phosphorylates the ITAM motifs of CD3G, CD3D, CD3E and CD247 enabling the recruitment of ZAP70. In turn ZAP70 phosphorylates LAT, which recruits numerous signaling molecules to form the LAT signalosome. The LAT signalosome propagates signal branching to three major signaling pathways, the calcium, the mitogen-activated protein kinase (MAPK) kinase and the nuclear factor NF-kappa-B (NF-kB) pathways, leading to the mobilization of transcription factors that are critical for gene expression and essential for T cell growth and differentiation. The T cell repertoire is generated in the thymus, by V-(D)-J rearrangement. This repertoire is then shaped by intrathymic selection events to generate a peripheral T cell pool of self-MH restricted, non-autoaggressive T cells. Post-thymic interaction of alpha-beta TR with the pMH complexes shapes TR structural and functional avidity.
Synonyms: TRBV66; TCRBV13S6A2T; TCRBV6S6
Gene: T-cell receptor variable (V) gene on chromosome 7 (142,469,537 to 142,470,013, forward strand). Ensembl gene ENSG00000211724.
Subcellular location: Cell membrane
Gene Ontology:
Biological process: cell surface receptor signaling pathway
Cellular component: plasma membrane
Homologues: Paralogues in human: TRBV6-5 (89% identical), TRBV6-8 (85% identical), TRBV6-7 (83% identical), TRBV6-1 (82% identical), TRBV6-2 (81% identical), TRBV6-4 (70% identical), TRBV10-2 (61% identical), TRBV10-1 (58% identical), TRBV10-3 (58% identical), TRBV27 (54% identical), TRBV24-1 (52% identical), TRBV25-1 (51% identical), and 39 more.
Diseases named in the same sentence as TRBV6-6 in open-access papers:
TRBV6-6 is named in the same sentence as 1 disease in open-access papers, as found by Europe PMC text mining. Sharing a sentence is not in itself a finding about the gene and the disease. The quoted sentences say what the papers report.
tumor (1 paper, 2021). "According to the bar graph, we found that RP11-334A14.8, RP4-738P11.4, TRBV6-6, LINC00668, and LINC00941 expression levels were higher in the relapsed tumor group than in the primary tumor group." (PMID 34532296, 2021). "We found that the expression of RP11-334A14.8, RP4-738P11.4, TRBV6-6, LINC00668, and LINC00941 was higher in the relapsed tumor group than in the primary tumor group." (PMID 34532296, 2021).